DKK1 (dickkopf Wnt signaling pathway inhibitor 1)
Diseases named in the same sentence as DKK1 in open-access papers (continued):
Sharing a sentence is not in itself a finding about the gene and the disease.
tumor (continued). "Our results suggested that DKK2 could not functionally substitute for DKK1 tumor-suppressive effect in EFT." (PMID 19247449, 2009). "In addition, using an EFT cell line SK-ES1 cells, we also demonstrated that the expression of DKK1 and DKK2 is mutually exclusive, and the ectopic expression of DKK1, but not DKK2, resulted in the suppression of tumor growth in immuno-deficient mice." (PMID 19247449, 2009). "Dkk-1 is also upregulated by other malignant cell lines, suggesting that serum Dkk-1 measurements may be useful for the evaluation of other types of malignancy, but the significance of Dkk-1 expression is not presently clear in tumours that do not affect bone." (PMID 17987039, 2007). "Specifically, only one out of the five ER−/PR+ tumours evaluated was DKK1+ (data not shown)." (PMID 17245340, 2007). "Because the antibody we used crossreacts with human and murine Dkk-1, we could not discriminate between tumour-derived and bone marrow-derived Dkk-1." (PMID 17876334, 2007). "However, whether DKK1 exerts systemic immune suppressive effects and/or generates a local immune suppressive environment at the primary tumor site has never been reported." (PMID 38659818, 2024). "Interestingly, iCCA is a cancer in which the canonical WNT signalling pathway is activated, suggesting that DKK1 may not be fulfilling its classical role of preventing WNT receptor activation in these tumours." (PMID 35924447, 2023). "However, the setting is highly complex and a clear oncogenic or anti-oncogenic role of DKK-1 in a given tumor type is not always clear, with a plethora of examples in which references to both sides may be found." (PMID 34451907, 2021). "In the current study, the negative association could reflect different biologic events possibly due to the fact that sclerostin activity is a part of a physiological process of bone remodeling, and is not secreted by cancer cells as opposed to DKK1 which is produced by tumor cells." (PMID 30227689, 2018). "Also, Zhu and coworkers demonstrated that MSCs have an inhibitory effect on tumor proliferation by identifiing that DKK-1 (dickkopf-1) which was secreted by MSCs, acts as a negative regulator of Wnt signaling pathway and is one of the molecules responsible for the inhibitory effect." (PMID 21545718, 2011). "Importantly, considering that DKK1 is preferentially expressed in tumours from women with a family history, but absent from important normal tissues, the protein could be targeted in a preventive vaccine for women at risk of developing the condition." (PMID 17245340, 2007). "However, because both tibias of mice inoculated with MDA-B02 cells presented with bone metastatic lesions, we could not analyse Dkk-1 levels in non-tumour-bearing legs from inoculated mice, which would have been the optimal control." (PMID 17876334, 2007). "When we compared anti‐LRP6 alone with the anti‐LRP6/DKK1 combination strategy, again there was variation in each treatment group, however FACS analysis revealed no changes in tumor burden." (PMID 36987921, 2023). "While these two tumor-associated clusters had gene expression profiles similar to that of the DCN-high tumor cell cluster 5, they did not express HB genes including GPC3, DLK1, and DKK1." (PMID 36008377, 2022). "In contrast, correlations between DKK1 and cytokines mainly deriving from or acting on lymphocytes such as IL2, IL4, or IL17 were weaker or absent in tumor tissues." (PMID 36539532, 2022). "The public database revealed a significant correlation between expression of DKK1 and FOXM1 mRNAs in the tumor lesions of PDAC and ESCC but not in EAC." (PMID 34117362, 2021). "The correlation between the ratios of tumor lesions with positive DKK1 and FOXM1 staining was confirmed, namely tumor lesions which highly expressed DKK1 were also positive for FOXM1, and tumor lesions not expressing DKK1 were negative for FOXM1." (PMID 34117362, 2021).
tumor (continued). "Previously, we showed that Dkk-1 overexpression in Ace-1 cells activated the noncanonical Wnt/JNK signaling pathway, resulting in increased tumor growth and the incidence of bone metastasis." (PMID 34437475, 2021). "In 119 tumor lesions of ESCC, there were close to 40% of cases positive for both DKK1 and CKAP4, about 30% of cases positive for either CKAP4 or DKK1, and approximate 30% negative for both." (PMID 33614703, 2020). "The two studies show that the expression of DKK1 and DKK3 was all significantly higher in the tumor lesions than in the nontumor regions." (PMID 33614703, 2020). "Serum dickkopf-1 (DKK1), a secretory antagonist of the Wnt signaling pathway, was highly expressed in HCC tissue and not detectable in the non-tumor liver." (PMID 32492896, 2020). "Vessel-specific LRP6 expression in tumors supports the idea that DKK1 and DKK2 expression does not affect tumor cell proliferation." (PMID 24091497, 2014). "Promising agents with bone-anabolic actions that do not directly inhibit tumor proliferation include TGFβ inhibitors and neutralizing antibodies against the WNT inhibitors DKK1 and sclerostin (which are negative regulators of bone formation)." (PMID 25757219, 2014). "DKK1 gene expression, for example, is decreased in GBM tumor samples, as compared with non-tumor brain tissues." (PMID 23516171, 2013). "Overall, our data are consistent with DKK-1 as a potent inhibitor of CCIC proliferation and tumor formation, but through a mechanism that is independent of canonical WNT signaling." (PMID 21317455, 2010). "However, since the correlation between AFP, GPC3, MDK, DKK1 and FNDC4 is not high, the sensitivity of FNDC4 as a tumor marker still needs further study." (PMID 38021165, 2023). "TE treatment significantly up-regulated DKK1 expression in CC15OT sample and CC16ANT (data not shown) which might account for its anti-tumor effects." (PMID 33552955, 2020). "Therefore, the effect of DKK1 on cell migration and invasion and on MMPs secretion was determined in the absence of TGF-β expression in tumor cells." (PMID 31568519, 2019). "In addition, the range of up- or downregulation in tumor versus control tissue was very high compared with KREMEN1 (not illustrated), indicating that Dkk1 is unlikely to damper Krm1 apoptotic activity in all cancers." (PMID 31069116, 2019). "DKK1 is a secreted protein that inhibits bone formation through inhibition of Wnt signaling pathway and has been shown to be highly expressed in NSCLC tumor material and serum from NSCLC patients as compared to patients with no tumor." (PMID 26353782, 2015). "If this is the case, increased DKK-1 expression in non-tumour derived tissue, as seen in our TMA, may have direct tumour promoting effects." (PMID 25182503, 2014). "In a study of ovarian cancer, the addition of DKK1 inhibitor DKN-01 or anti-PD-1 therapy did not enhance the antitumor effect of PORCN inhibitor CGX-1321, although the use of CGX-1321 monotherapy significantly reduced tumor burden and increased CD8+ T-cell levels." (PMID 39253139, 2024). "As we demonstrated in this study, ectopic expression of DKK1 in EFT cells resulted in the inhibition of tumor growth in SCID mice, whereas DKK2 expression did not and even possibly accelerated tumor growth in vivo, demonstrating that DKK2 does not act as a counterpart of DKK1." (PMID 19247449, 2009). "However, it remained unclear how DKK-1, considered predominantly an antagonist of β-Catenin-dependent Wnt signaling, could inhibit MΦ-induced invasion which was mediated by non-canonical Wnt signaling via activation of JNK in the tumor cells." (PMID 24185202, 2013).
cancer (320 papers, 2007 to 2026). A tumor composed of atypical neoplastic, often pleomorphic cells that invade other tissues. "In our study, we used DKK1 instead of cardamonin, because cardamonin is mostly associated with inhibiting Wnt to combat cancer, which is outside the scope of this study." (PMID 40837704, 2025). "DKK1 has been reported to show increased expression in patients with various types of cancer and to be associated with malignancy of cancer." (PMID 40025612, 2025). "In this study, mRNA sequencing shows that T6I-29-1A significantly downregulates DKK1, a paracine factor associated with metastasis in other cancers." (PMID 38978585, 2024). "We show that DKK1 is expressed by cancer-associated fibroblasts (CAFs) infiltrating primary tumors, and at higher levels by bone cells." (PMID 38659818, 2024). "DKK1 is associated with an immune-suppressive microenvironment of various cancers, making it a potential indicator of immune-therapeutic resistance." (PMID 39513892, 2024). "Dkk1 is a secretory protein that is typically an antagonist to Wnt/β-catenin, which has been widely linked with various cancer entities, including BC." (PMID 38254908, 2024). "DKK1 is dysregulated in various cancers, suggesting its potential as a diagnostic biomarker and therapeutic target for multiple cancer types." (PMID 38012711, 2023). "Together, these results demonstrated that DKK-1 increased PCa growth, decreased cancer-induced intramedullary woven bone formation, and caused dramatic bone destruction in vivo." (PMID 38067123, 2023). "The present study indicated that the cancer-promoting role of DKK-1 in PCa bone metastases was associated with increased growth of bone metastases, reduced bone induction, and altered signaling through the canonical WNT-independent pathway." (PMID 38067123, 2023). "The secreted DKK1 from BRCA1-deficient cancer cells on the other hand confronts immune cells, assisting the apoptotic resistance." (PMID 35517499, 2022). "Hypermethylation of promoter-associated CpG islands of DKK1 has been shown to induce transcriptional inactivation of DKK1, thereby suppressing the inhibition of the Wnt pathway in cancer." (PMID 35625973, 2022). "Elevated levels of DKK-1 in a variety of tumors are associated with poor prognosis, suggesting that DKK-1 represents a common malignant tumor biomarker." (PMID 35892678, 2022). "DKK1 encodes a secreted protein that promotes the proliferation, invasion, and growth of cancer cell lines." (PMID 36712848, 2022). "Subsequently, we investigated the association of DKK1 expression with the survival time of patients with different cancers." (PMID 34899842, 2021). "Beyond the potential to be a diagnostic indicator, DKK1 has been viewed as a promising target for anti-cancer therapy due to its cancer-promoting activity existing in preclinical cancer models." (PMID 34093545, 2021). "Differential DKK1 expression was associated with poor overall survival (OS) in several types of cancer (p < 0.05)." (PMID 34899842, 2021). "Dickkopf-related protein 1 (DKK-1) has a diagnostic and prognostic value in various malignant tumors." (PMID 33921232, 2021). "Quiescence in lung metastatic cancer cells is caused by autocrine DKK1, which leads to the downregulation of certain cell surface markers recognized by NK cells, allowing cancer cells to evade innate immunity." (PMID 31616443, 2019). "DKK1 is found elevated in serum from patients affected with various types of cancers and in some instances, it is considered a diagnostic and prognostic biomarker." (PMID 30028084, 2018). "Elevated serum DKK1 has been found to be associated with worse survival in cancers from multiple organs including the pancreas, stomach, liver, ovary, bile duct, bladder, prostate, breast, cervix and esophagus." (PMID 29108326, 2017). "Dysregulation of DKK1 has been associated with bone pathologies and has now emerged as a potential biomarker of cancer progression and prognosis for several types of malignancies." (PMID 27367730, 2016).
cancer (continued). "The TaqMan assays confirmed the observation that Dkk1 is one of the most prominent candidates with expression in colon mucosa altered in association with inherited cancer predisposition and WD*." (PMID 24204690, 2013). "Differential gene expression analysis showed that the resistance of the CAL27 cell line to cisplatin, an anti-cancer chemotherapy drug, is associated with the expression level of DKK-1." (PMID 20920327, 2010). "Considering the activity of Dkk2 and -4, it is interesting to note that only Dkk1 has been implicated thus far in cancer-associated bone lesions." (PMID 17971207, 2007). "Interestingly, cancer-associated fibroblasts (CAFs) are a primary source of DKK1 in the stroma, where they facilitate immune evasion." (PMID 42123366, 2026). "DKK1 is a secreted glycoprotein that is classically known as an inhibitor in the Wnt/β-Catenin pathway, although it demonstrates non-canonical activities that that are implicated in pathogenic progression across many cancers." (PMID 38978585, 2024). "Dkk1 has regulatory functions in the wnt signaling pathway and metalloproteinase expression (Mmp-1, -2 and -9) and has been associated with a poor prognosis in several cancers." (PMID 37298091, 2023). "Enhanced cancer progression by DKK-1 was associated with increased cell proliferation, up-regulation of NF-kB/p65 signaling, inhibition of caspase-dependent apoptosis by down-regulation of non-canonical WNT/JNK signaling, and increased expression of epithelial-to-mesenchymal transition genes." (PMID 38067123, 2023). "In our study, we found that DKK1 secreted by BRCA1-deficient cancer cells could inhibit CD8+ T cells proliferation, which impaired CD8+ T cells activation." (PMID 35517499, 2022). "Meanwhile, the Wnt antagonist DKK1 (Dickkopf-1) has been implicated in the modulation of immune cell activities as well as the immunosuppressive microenvironment in cancers and has become a promising target for cancer immunotherapy." (PMID 35785179, 2022). "DKK1, as a critical component in the canonical Wnt pathway, is linked to a variety of cancers." (PMID 35355709, 2022). "Chronic inflammation is a well-acknowledged risk factor of cancers, we hypothesized that DKK1 influenced cancer prognosis through immune cell infiltration." (PMID 34899842, 2021). "Given that elevated levels of DKK1 were found in blood of FA‐deficient mice and that FA is a cancer prone disease, DKK1 might be of interest for FA." (PMID 30028084, 2018). "Recently, an increasing number of studies have demonstrated the potentially diagnostic and/or prognostic values of DKK-1 in varied cancers, such as lung cancer, gastrointestinal cancers, pancreatic cancer, and hepatocellular carcinoma, as well as rheumatic disorders, including RA and AS." (PMID 28373995, 2017). "Over-expression of DKK1 is found in most human cancers, suggesting that it could serve as a useful diagnostic predictor for PC." (PMID 26101916, 2015). "DKK1 has been linked to other attributes specific to cancer cells." (PMID 17245340, 2007). "Finally, the triggers underlying high DKK1 expression in cancer remain to be defined." (PMID 36539532, 2022). "Additionally, some studies implied that Dkk-1 could serve as a modulator to alter the cancer metastasis-associated microenvironment." (PMID 33384994, 2020). "Therefore, DKK1 may be a good candidate protein to monitor cancer both as a diagnostic tool and as a prognostic indicator." (PMID 27367730, 2016). "In summary, by integrating preclinical insights with current clinical data, this review provides a strategic roadmap for advancing DKK1-targeted therapies in cancer." (PMID 42122171, 2026).
cancer (continued). "The Wnt/β-catenin pathway plays a central role in cancer progression, and intensive research has found DKK1 as a Wnt/β-catenin pathway inhibitor." (PMID 40282454, 2025). "Expression of DKK1 has been positively correlated with the expression of VEGF in various cancer types." (PMID 39795613, 2025). "Targeting of DKK1 in drug discovery has been an increasing area of interest in cancer therapy, with candidates progressing through clinical studies that are currently in phase 1 and phase 2 trials." (PMID 40394415, 2025). "On the other hand, in breast cancer, cancer cells can develop trastuzumab resistance by downregulating DKK1 and activating the Wnt signaling pathway." (PMID 39795613, 2025). "DKK1, known as a modulator of Wnt signaling, is frequently overexpressed in various types of cancer and often tied to poor clinical outcomes due to immunosuppressive effects." (PMID 39941712, 2025). "Upregulation of DKK1 in EAC cell lines enhances cancer cell proliferation as well as cell invasion and migration." (PMID 39795613, 2025). "Originally identified as a protein involved in embryonic development, DKK1 is now thought to play a role in cancer progression by creating an environment where cancer cells can thrive and multiply." (PMID 39788945, 2025). "Dickkopf-1 (DKK1) is a soluble inhibitor of the Wnt/β-catenin pathway, primarily recognized for its role in bone homeostasis and cancer-induced osteolytic bone disease." (PMID 39885132, 2025). "DKK1 functions as an inhibitor of the Wnt/β‐catenin signaling pathway, participating in the pathogenesis of diverse diseases, such as cancer, hypertension, neurodegenerative disorders, diabetic nephropathy, and arthritis." (PMID 41320970, 2025). "Since IL-6 and CCL2 are representative markers of inflammatory fibroblasts, our results indicate that cancer cell-derived DKK1 induces lung fibroblasts to adopt an inflammatory phenotype." (PMID 40025612, 2025). "Confirming the microarray analysis, DKK1 was expressed in the cancer epithelial cells in HER2+ and TNBC, while it was detected at much lower levels in ER+ and in the normal epithelial cells." (PMID 39885132, 2025). "Following the confirmation of the importance of cancer cell-fibroblast interactions in the protumorigenic activity of DKK1, the fibroblast traits modulated by DKK1 were further analyzed." (PMID 40025612, 2025). "Conversely, cancer tissue with blocked DKK1 function, achieved by administering a DKK1-neutralizing antibody, exhibited increased collagen and α-SMA protein levels." (PMID 40025612, 2025). "A meta-analysis also demonstrated that increased DKK1 expression correlates with shorter progression-free survival, disease-free survival, and time to recurrence in various cancers, including digestive system cancers." (PMID 40804038, 2025). "For example, the downstream pathways of DKK1 can modulate cancer cells to obtain resistance to drugs, and immune modulation by DKK1 can support resistance to immunotherapy." (PMID 40025612, 2025). "It is our contention that ID1 is a strong regulator of DKK‐1 in cancer cells and implicates known VM pathways (P13K/AKT and ERK) to promote extracellular matrix (ECM) remodelling and ultimately VM formation." (PMID 40116596, 2025). "Emerging evidence indicates that DKK1 is involved in T cell differentiation and induces cancer evasion of immune surveillance by accumulating MDSCs." (PMID 40394415, 2025). "DKK1 thus inhibits the Wnt signaling pathway, which is involved in cell proliferation and survival and is abnormally activated in cancer cells making cells less responsive to these signals." (PMID 40109582, 2025). "Collectively, these results suggest that the c-JUN pathway in lung fibroblasts can be activated by DKK1, contributing to the activation of inflammatory fibroblast traits and cancer cell-fibroblast interaction." (PMID 40025612, 2025).